SEMA3A (semaphorin 3A)
Diseases named in the same sentence as SEMA3A in open-access papers (continued):
Sharing a sentence is not in itself a finding about the gene and the disease.
cancer (continued). "In fact, a previous study indicated that SEMA3A upregulation promotes tumorigenesis and leads to poorer overall prognosis in adult cancers." (PMID 36497424, 2022). "Upregulation of MS4A1, IGLL1, RAG1, and SEMA3A resulted in significantly decreased survival in pediatric cancer patients." (PMID 36497424, 2022). "Differential expression analysis with the limma-voom pipeline highlighted multiple genes, CR2, MS4A1, and SEMA3A, which should be further analyzed, given their prevalence among multiple cancer types." (PMID 36497424, 2022). "Recent studies also found that SEMA3A regulates the behavior of cancer cells and is highly expressed in HCC, which correlates with metastatic potential and cancer aggressivity." (PMID 36551769, 2022). "SEMA3A was downregulated in all the cancers in which it was differentially expressed, while the regulation of CR2 and MS4A1 varied according to cancer type." (PMID 36497424, 2022). "Mechanistic analysis revealed that AuNPP-FA reinforced the expression and production of semaphorin 3A (SEMA3A) in cancer cells, which further led to the suppression of Smad2/3 signaling cascade in ECs." (PMID 36439137, 2022). "CCLE was used to assess the expression distribution of EME1/HNRNPAB/PLAUR/SEMA3A in pan-cancer cell lines." (PMID 36091160, 2022). "Overexpression of Sema3A inhibited cancer metastatic dissemination induced by antiangiogenic treatment in mice via the suppression of EMT." (PMID 35775491, 2022). "The GSCA database was used to examine the role of EME1/HNRNPAB/PLAUR/SEMA3A in 10 cancer pathways and found that EME1 was mainly involved in the activation of apoptosis, cell cycle and DNA damage response and inhibition of RAS/MAPK pathways." (PMID 36091160, 2022). "Knocking down Sema3A results in a decelerating of cancer cell proliferation and improved pain behavior." (PMID 36231105, 2022). "Multiple studies have shown that reduction of semaphorin 3A expression occurs in later stages of cancers (including breast and prostate) and that exogenous semaphorin 3A leads to reduced metastasis and angiogenesis." (PMID 34270956, 2021). "Dysregulation of semaphorin 3A or semaphorin 3C has been implied for cardiovascular disease and various cancers." (PMID 34270956, 2021). "The paucity of Sema3A staining in normal tissue and the gradual increment in the area and intensity of the staining as cancer transforms to more aggressive forms clearly indicates that Sema3A has a crucial role in this transformation." (PMID 33546237, 2021). "Sema3A alters cancer cell behavior directly by affecting cell migration and growth, and is frequently overexpressed in glioblastoma, pancreatic, lung, and prostate cancer." (PMID 32192122, 2020). "Recent studies suggest that semaphorin 3A (Sema3A), a member of the semaphorin family, is involved in the development of several cancers." (PMID 32192122, 2020). "SEMA3A is a member of the semaphorin family of proteins that play a role in many developmental processes as well as in cancer progression." (PMID 32283808, 2020). "Experimental evidence proved sempahorins’ role in the modulation of the immune response in various cancers, with particular reference to Sema3A and Sema4D." (PMID 31052281, 2019). "It was found that class 3 semaphorins (Sema3A, Sema3B, and Sema3F) decreased with the transition from in situ to invasive cancer and Sema3A expression was only significantly reduced once invasion had occurred." (PMID 31929841, 2019). "In fact, Sema3A-overexpressing U87MG cells were poorly tumorigenic in mice, which was associated with a lower abundance of cancer blood vessels." (PMID 31052281, 2019). "Cumulative recent findings define Sema3A as a potent anti-angiogenic and anti-malignant molecule in different types of cancer." (PMID 30598022, 2018). "Another recent study has identified Sema3A as a necessary molecule for the maintenance of cancer stem-like cells in the lungs." (PMID 30134791, 2018).
cancer (continued). "Together with previous findings, our results demonstrate that SEMA3A can induce apoptosis through different mechanisms in cancers, including HNSCC." (PMID 26755661, 2016). "The clinicopathological significance of SEMA3A expression in HNSCC prompted us to further dissect the possible biological roles of SEMA3A in cancer progression by gain-of-function assays and genetic approaches." (PMID 26755661, 2016). "We found that one class 3 semaphorins family member, Sema3A, had a crucial role in carcinoma development." (PMID 27351132, 2016). "Specifically, the transcriptional expression of SEMA3A is negatively EZH2-dependent in both human cancer and mouse model in vivo." (PMID 26043758, 2015). "On the other hand, a previous study found that Sema3A counteracted chemotherapy-induced activation of epithelial-mesenchymal transition (EMT) by improving cancer tissue oxygenation and extending the vascular normalization." (PMID 26043758, 2015). "Of note, and in this context, Sema3A and Sema3F have been reported to favour the normalization of cancer vasculature and impair metastatic dissemination." (PMID 26311294, 2015). "More importantly, significantly higher expressed SEMA3A was previously reported in chemosensitive cancers than in chemoresistant tumors." (PMID 26043758, 2015). "While this suggests inherent or genetic differences between patients are the cause of the variations in severity in patient reactions, the involvement of SEMA3A requires further validation using large numbers of patients with a unique cancer type." (PMID 20701746, 2010). "The interaction between NRP1 and its ligands, such as Sema3A, can influence the expression and function of immune checkpoint molecules such as programmed cell death protein 1 (PD-1) on T cells, affecting immune responses in cancer and autoimmunity." (PMID 40277760, 2025). "We analyzed differences of SEMA3A expression between cancer subtypes." (PMID 38263416, 2024). "For SEMA3A, SEMA3C, and SEMA7A as well as the semaphorin receptor neuropilin, there was a clear trend where the expression above the cutoff was associated with worse survival for all three cancers." (PMID 37719704, 2023). "Previous studies reported that semaphorins members play important regulatory roles in the development of the nervous system (Sema3A, 3F, 4D, 6C, 6D, 7A), immune system (Sema4D), reproductive systems (Sema3), cancer progression (Sema3A, 4D, 6D) and the vascular system (Sema3A, 3E, 4D, 6D)." (PMID 36010604, 2022). "Of particular note, SEMA3A was under-expressed in all identified cancer types compared to their healthy tissue samples, which may suggest that reactivation of SEMA3A is critical for cancer progression." (PMID 36497424, 2022). "In addition, Sema3A affects the cytoskeleton and cancer cell survival by negatively regulating LIMK/p-cofilin pathway–dependent actin polymerization." (PMID 35775491, 2022). "Sema3A is often up-regulated in some cancers but down-regulated in others." (PMID 32102436, 2020). "This logic may lead to the consideration of SEMA3A as a potential therapeutic for the treatment of cancer, specifically in combination with bevacizumab." (PMID 32842711, 2020). "Therefore, it is worthy to investigate the therapeutic potentials of anti-SEMA3A antibody for treatment of cancers." (PMID 31205625, 2019). "It is important to note that the levels of Sema3A in different types of cancer have to be evaluated concomitantly with its receptors and the levels of competitive receptor-binding molecules, such as Sema4A (binds NRP-1), and known Plexin A1 ligands, namely - Sema3C, Sema3F, and Sema6D." (PMID 30134791, 2018).
cancer (continued). "Several reports have demonstrated the importance of Sema3A in cancer development and progression." (PMID 30134791, 2018). "However, downregulation of SEMA3A has been observed in many cancers and correlates with clinicopathological features." (PMID 29649113, 2018). "Moreover, it has been shown that Sema3A expression inversely correlated with an increasing degree of malignancy in different types of cancer, including ovarian, breast, gastric, and non-small cell lung cancer, when compared with corresponding normal tissue." (PMID 30134791, 2018). "Moreover, the observed progressive decrease of Sema3A expression in endothelial cells starting from the pre-malignant lesions to actual tumors suggested its prognostic biomarker prospective for cancer progression." (PMID 30598022, 2018). "Moreover, recently published research showed that a downregulation of Sema3A expression promoted cancer metastasis." (PMID 30598022, 2018). "SEMA3A is a member of the semaphorin family, which comprises soluble and membrane bound proteins that play a role in neuronal development, organogenesis, angiogenesis and cancer progression." (PMID 29649113, 2018). "In GBM, semaphorin3A (Sema3A)-NRP1 signaling mediates the invasion of cancer cells." (PMID 29088765, 2017). "Furthermore, the therapeutic efficacy of SEMA3A-targeted delivery against HNSCC was confirmed in a cancer xenograft model." (PMID 26755661, 2016). "In summary, we have demonstrated for the first time that SEMA3A expression is down-regulated to low levels in most human HNSCC and that the over-expression of SEMA3A suppresses the proliferation, invasion and induction of apoptosis of cancer cells both in vitro and in vivo." (PMID 26755661, 2016). "We found that compared with normal tissues, Sema3A was distinctly increased in carcinoma issues." (PMID 27351132, 2016). "Therefore, Sema3A is important in diseases characterised by angiogenesis, such as cancer." (PMID 40634736, 2025). "Sema3A may appear to be an ambiguous target for the development of cancer therapies." (PMID 32102436, 2020). "The interactions between NGF and semaphorin 3A could induce cancer cell apoptosis." (PMID 31839752, 2019). "The LIMK/p-cofilin signaling pathway links the limited Sema3A signal to lamellipodia formation and mediates EMT via cytoskeletal actin remodeling in cancer cells." (PMID 35775491, 2022). "Further investigation confirmed DNA hypomethylation and upregulation of SEMA3A tumor suppressor gene, promoter of which was shown to be bound by DNMT3A in cancer cells in our previous studies." (PMID 36296971, 2022). "The results showed a trend of a higher expression level in cancer tissues for ISG15, CAPN7, SEMA3A, and DYRK4 genes." (PMID 35008303, 2021). "Nevertheless, SEMA3A, SEMA3C, and SEMA3F primarily showed up-regulated expression, and the rest of the SEMA3s mainly showed down-regulated expression in the 16 tested cancer types." (PMID 32241267, 2020). "SEMA3A, SEMA3D, and SEMA3E showed relatively lower level of expression averaged across all cancer types compared to the rest of the SEMA3 family members.i.e., SEMA3B, SEMA3C, SEMA3F and SEMA3G, where SEMA3F had the highest expression." (PMID 32241267, 2020). "Sema3A, which shares NRP-1 receptor with Sema4A, was identified as a potential anti-cancer semaphorin with anti-angiogenic signaling." (PMID 30598022, 2018). "Semaphorin 3A and Netrin-G1 could promote PDAC progression through their effects on cancer cells and immune cells." (PMID 40777309, 2025). "Additionally, cancer cells promote monocyte recruitment through the release of chemotactic signals such as VEGFA, CCL2, CXCL12, semaphorin 3A (SEMA3A)." (PMID 34680425, 2021). "Unlikely, at present only preclinical findings support the use of small molecules inhibiting Sema3A (SM-216289, Xanthofulvin; SM-345431, Vinaxanthone) for the treatment of disease not including cancer." (PMID 33858502, 2021).
cancer (continued). "Studies have also substantiated the role of SEMA3A as a regulator of cell apoptosis in both cancers and non-cancerous diseases." (PMID 34821196, 2021). "In conclusion, our data demonstrate that targeting NRP-1 in cancer, using antagonistic anti-NRP-1 Nbs that prevent the interaction with Sema3A, delays growth of CRC tumors and extends the survival through a shift in the MHC-IIhigh/MHC-IIlow ratio and an activation of CRC-specific CD8+ T cells." (PMID 33266104, 2020). "In conclusion, our data demonstrate that targeting NRP-1 in cancer, using antagonistic anti-NRP-1 Nbs that prevent the interaction with Sema3A, delays growth of CRC tumors and extends survival through a shift in the MHC-IIhigh/MHC-IIlow ratio and an activation of CRC-specific CD8+ T cells." (PMID 33266104, 2020). "Among the 7 SEMA3 gene members, expression levels of SEMA3A and SEMA3C, SEMA3C and SEMA3F showed the highest correlation across all 31 cancer types, suggesting they may share some common functions." (PMID 32241267, 2020). "In contrast to SEMA3A, SEMA3C, and SEMA3F, the rest of the SEMA3 family members showed prominent down-regulation and they all negatively correlated with cancer stem-cell-like features (RNAss and DNAss) across cancer types." (PMID 32241267, 2020). "Further analysis of 21 paired NSCLC samples showed a significant upregulation of miR-362 expression and downregulation of Sema3A in cancer tissues compared with the matched noncancer tissues." (PMID 30155491, 2018). "Sema3A’s function in cancer is still unclear and needs to be defined in vitro using cancer cell lines and in vivo using mice lacking Sema3A and/or corresponding individual receptor expression generated by different techniques that are currently available." (PMID 30134791, 2018). "However, the role of SEMA3A in cancer pathway activity was not significant, except in the EMT pathway." (PMID 36091160, 2022). "However, the presented data have been controversial with regards to the positive or negative effects of Sema3A overexpression in certain types of cancer." (PMID 30134791, 2018). "However, the means by which extracellular cues, such as Sema3A, modulate changes in cell-substratum adhesion strength to alter cancer cell migration speed are not clearly elucidated." (PMID 28182100, 2017). "Therefore, it can be speculated that besides direct inhibitory effects of Sema3A-Nrp1 interaction on PDGF-induced HASMC proliferation, Nrp1 might compete with PDGFR to bind its ligand which, unlike cancer studies, further weakened the cellular function." (PMID 27791986, 2016).
retinopathy (7 papers, 2013 to 2024). "In addition, neuron-derived Sema3A provokes microglial chemotaxis through Nrp1 and can contribute to inflammation associated with retinopathy." (PMID 32781674, 2020). "For instance, during the progression of retinopathy, secretion of the neuron-derived Semaphorin 3A (SEMA3A) by senescent retinal neuronal cells contributes to propagating paracrine senescence." (PMID 37830555, 2023). "Sema3A modulation is a promising mechanism of action that has been shown to reduce ischaemia in a mouse model of oxygen-induced retinopathy." (PMID 35978329, 2022). "Silencing expression of Sema3A in a mouse model of oxygen-induced retinopathy has been shown to maintain neuroretinal function." (PMID 35978329, 2022). "Collectively, these studies indicate that the Sema3A–Nrp-1 signaling axis is a promising therapeutic target for retinopathy." (PMID 35045890, 2022). "Sema3A can also promote apoptosis in retinal neurons, contributing to neurodegeneration in retinopathy." (PMID 32781674, 2020). "In retinopathy models, mRNA expression of the inflammatory cytokines IL-1β and TNFα, as well as Sema3a, increased significantly compared to controls." (PMID 29975739, 2018). "Moreover, intravitreal administration of soluble Nrp-1, which neutralizes Sema3A bioactivity, reduces microglial infiltration and pathological neovascularization in retinopathy." (PMID 35045890, 2022). "Furthermore, recent data show that administration of the anti-Sema3A agent BI 764524 in a mouse model of oxygen-induced retinopathy significantly reduces avascular area size and had a beneficial effect on intraretinal oedema and ischaemia in a retinal vein occlusion mouse model." (PMID 35978329, 2022). "In a mouse model of oxygen-induced retinopathy that mimics proliferative DR, NGFR-dependent inflammation leads to ischemia and pathological angiogenesis via Semaphorin 3A." (PMID 39347501, 2024).
infection (6 papers, 2016 to 2024). The state of being infected such as from the introduction of a foreign agent such as serum, vaccine, antigenic substance or organism. "After infection with a lentivirus containing Sema3A shRNA, immunoblotting analysis confirmed the knockdown efficiency of Sema3A." (PMID 37310417, 2023). "To specifically investigate the role of SEMA3A in cell apoptosis, we performed a flow cytometric analysis 48 hours after infection." (PMID 26755661, 2016). "We constructed AAV9‐ENT vectors (based on adeno‐associated virus 9 (AAV9) serotype modification and enhanced the infection efficiency of vascular endothelial cells) carrying Sema3A‐shRNA under the ICAM2 promoter; we then, we delivered these AAV9‐ENT vectors through the tail veins of mice." (PMID 37310417, 2023).
bone disorder (3 papers, 2017 to 2024). "This will facilitate the understanding of Semaphorin 3A in skeletal biology and shed new light on the modulation and potential treatment in the bone disorders." (PMID 28293171, 2017). "Similarly, Sema3A may be a marker for bone disorders such as osteoporosis." (PMID 28293171, 2017).